ERBB2 (erb-b2 receptor tyrosine kinase 2)
Diseases named in the same sentence as ERBB2 in open-access papers (continued):
Sharing a sentence is not in itself a finding about the gene and the disease.
breast cancer (continued). "Afatinib has demonstrated preclinical activity in human epidermal growth factor receptor HER2 (ErbB2)-positive and triple-negative xenograft models of breast cancer, and clinical activity in phase I studies." (PMID 22763464, 2012). "Recent molecular profiling has identified six major subtypes of breast cancer: basal-like, ErbB2-overexpressing, normal breast epithelial-like, luminal A and B, and claudin-low subtypes." (PMID 22514728, 2012). "Yet another important marker in the evaluation of breast cancer is the human epidermal growth factor receptor-2 (HER2; c-erbB-2), which is a member of the epidermal growth factor receptor family." (PMID 22482085, 2012). "Although published data support a significant biological role for the AR and ErbB2 signaling in molecular apocrine breast cancer, there is currently limited information regarding other functionally important genes and pathways in this disease." (PMID 22817771, 2012). "Collectively these data argue that the integrin/c-Src/FAK signalling network is a key regulator of the proliferative capacity of both ErbB2 and PyVmT mammary tumour cells." (PMID 22373082, 2012). "Over-expression of ErbB2 is found in almost 20% of breast cancers, and this results in proliferative and anti-apoptotic signalling." (PMID 24281706, 2012). "HER-2/neu (HER2), also known as c-erbB-2, is a biomarker assayed in tissue biopsies from women diagnosed with malignant breast tumors." (PMID 22570650, 2012). "Among the top twelve genes in this ranking system, we have previously studied the transcriptional regulation of AR and ErbB2 in molecular apocrine breast cancer." (PMID 22817771, 2012). "In particular, several groups have reported a correlation between FAK and human epithelial growth factor receptor (ErbB2, Neu) overexpression in ErbB2-positive human breast cancer." (PMID 22373082, 2012). "We show by RNA-seq that PADI2 mRNA expression is highly correlated with HER2/ERBB2 (p = 2.2 × 106) in luminal breast cancer cell lines." (PMID 23110523, 2012). "MiR-125a over-expression impaired the anchorage-dependent growth, migration and invasion of breast cancer cells by down-regulating ERBB2 and ERBB3 in the ERBB2-dependent SKBR3 cell line." (PMID 22768249, 2012). "Suppression of ErbB2-signaling by lapatinib in ER(−) breast cancer resulted in activation of FOXO3a and caveolin-1, leading to activation of ER-signaling." (PMID 22924092, 2012). "Treatment with antiprogestin or MEK inhibitor abrogated expression of SUMO-sensitive PR target-genes and inhibited proliferation in BT-474 (estrogen receptor (ER)+/PR+/ERBB2+) breast cancer cells." (PMID 22697792, 2012). "Hemler and coworkers showed that adhesion of human Erb2-positive breast cancer cells to laminin-5 provided significant resistance to trastuzumab and lapatinib, an antibody and a small-molecule, respectively, that target ErbB2." (PMID 22567280, 2012). "Since we have most recently found that C-18 is exquisitely sensitive for the detection of MembErbB-2 and NuclErbB-2 in breast cancer cells by IF, we decided to assess ErbB-2 levels and cellular localization by IF in our TMAs." (PMID 22356700, 2012). "Breast cancer is one of the most common cancers in women, resulting from gene amplification and/or overexpression of some oncogenes like HER2/neu (also known as ErbB2) and oestrogen receptors." (PMID 22007260, 2012). "Activation of FAK has also been observed in human breast cancer cell lines expressing elevated levels of ErbB2." (PMID 22373082, 2012). "Here we show that PTPN13 regulates a new signaling complex in breast cancer consisting of ErbB2, Src, and EphrinB1." (PMID 22279592, 2012). "We therefore tested the PR- and MAPK-dependent regulation of selected genes co-associated with ERBB2 overexpression and SUMO-sensitivity (above) in HER2-amplified but SR-positive BT-474 breast cancer cells that contain constitutively activated MAPKs." (PMID 22697792, 2012).
breast cancer (continued). "Elevated expression of FAK has been previously implicated as an important determinant in both the initiation and the progression of ErbB2-positive breast cancers." (PMID 22373082, 2012). "The frequent copy number gains (38%) and amplification (29%) of ERBB2 in this study are consistent with previous studies on breast cancer." (PMID 22938721, 2012). "Overexpression and gene amplification of ErbB2 are frequently observed in human malignancies, in particular in 25–30% of primary human breast cancers." (PMID 22007291, 2012). "ErbB2 (Her2) amplification/over-expression occurs in 20-30% of breast cancers resulting in aggressive tumor behavior and poor prognosis." (PMID 22279592, 2012). "A full-length form of nuclear ErbB-2 is involved in COX2 transcriptional regulation via transactivating COX2 gene promoter in breast cancer cells." (PMID 22520625, 2012). "ErbB2 is an important initiator of mammary tumorigenesis with more than 30% human breast cancers exhibiting ErbB2 amplification and overexpression." (PMID 23028720, 2012). "Although the ERBB2 gene is frequently amplified in HER2+ breast cancer, upregulation of the TFAP2B gene provides an additional mechanism for over-expression of the ErbB2/HER2 protein." (PMID 22343619, 2012). "The human ERBB2 proto-oncogene is widely considered a key gene involved in human breast cancer onset and progression." (PMID 22489125, 2012). "Taken together, these findings indicate that PADI2 is predominantly expressed in luminal epithelial cells, and that there appears to be a strong relationship between PADI2 and HER2/ERBB2 expression in breast cancer." (PMID 23110523, 2012). "Collectively these observations argue that while FAK contributes to ErbB2 tumour cell proliferation, it is ultimately dispensable for ErbB2 mammary tumour initiation and progression." (PMID 22373082, 2012). "Amplification and overexpression of the ERBB2 oncogene in RAR-G13 (17q12) is known to be associated with high recurrence rates and reduced breast cancer survival." (PMID 22938721, 2012). "Neu (HER2/ErbB2) is overexpressed in 25% to 30% of human breast cancer, correlating with a poor prognosis." (PMID 22314082, 2012). "To evaluate the role of FAK in ErbB2 mammary tumour progression, we initially interbred the MMTV-activated ErbB2 strain (NDL2-5) with separate strains of mice bearing MMTV-Cre and conditional FAK alleles." (PMID 22373082, 2012). "Most importantly, the regressions seen in the transgenic model recapitulated the regressions seen in the ERBB2-positive breast cancer patients." (PMID 22621282, 2012). "Several studies have shown that ERBB2/HER2 and the basal subtype of breast cancer are the predominant types of breast cancer that metastasize to the brain." (PMID 22429330, 2012). "A recent study investigated the antitumor effects of trastuzumab (a monoclonal antibody against EGFR-2) in combination with glycolysis inhibitor 2-DG in ErbB2-positive breast cancer." (PMID 22844340, 2012). "We found that EphrinB1 and ErbB2 co-precipitate from lysates derived from breast cancer cell lines as well as HaCaT cells." (PMID 22279592, 2012). "The transgenic MMTV-NEU-NT mouse is a suitable and relevant model for ERBB2-driven human breast cancer." (PMID 22621282, 2012). "Differential expressions of miRNAs indicated different level of proliferations corresponding to 6 intrinsic breast cancer subtypes: luminal A, luminal B, basal-like, normal-like, and ERBB2." (PMID 23031749, 2012). "The difficulty in identifying initiation processes in tumors in vivo is typified by the ERBB2 amplification in breast cancer." (PMID 23181561, 2012). "Collectively these observations suggest that targeting both Pyk2 and FAK will be required to effectively eliminate ErbB2-dependent mammary tumours." (PMID 22373082, 2012). "Conclusively, the group of Muller demonstrated that AKT1 induced tumor growth, while AKT2 promotes metastasis of ErbB2-induced breast cancer in vivo." (PMID 23167739, 2012).
breast cancer (continued). "A confrontation of two IHC definitions of basal breast cancers in a series of 3744 cases revealed that the five-biomarker definition (ER, PR, ERBB2, CK5/6 and EGFR) had superior prognostic value than the TN one." (PMID 22082486, 2012). "However, the finding that human ErbB2 polymorphisms can affect breast cancer prevalence suggests that the study of transmembrane activating ErbB2 mutations in animals (in the absence of amplification/over-expression) may prove beneficial in the context of human disease." (PMID 22279592, 2012). "Another important feature of the activated ErbB2 mammary tumour mouse model is that 60% of tumour-bearing animals will develop metastatic lesions to the lung." (PMID 22373082, 2012). "It was also demonstrated that the assignment of basal-like and ERBB2+ (HER2+) breast cancers to the poor-prognosis groups by first-generation gene signatures is determined mainly by high expressions of proliferation-related genes." (PMID 22225836, 2012). "While these studies indicate the importance of FAK in the initiation phase of ErbB2 mammary tumour progression, acute deletion of FAK in established tumour cells also impacts on their ability to proliferate in both in vitro and in vivo settings." (PMID 22373082, 2012). "In vitro studies have, however, demonstrated that a combination of trastuzumab and 17-AAG led to enhanced down-regulation due to lysosomal degradation of ErbB2 in ErbB2-overexpressing breast cancer cell lines." (PMID 24281706, 2012). "ERBB2, amplified in approximately 15-20% of breast cancers, is a well-known, targetable membrane-bound growth-factor receptor that is effectively inhibited by trastuzumab in clinical practice." (PMID 23383675, 2012). "More recently, the Hemler laboratory reported that resistance of ErbB2-positive breast cancer cells to anti-Erb2 agents can be overcome by disrupting cell adhesion." (PMID 22567280, 2012). "Similar to CHN2 and RGS2, we predict that a significant number of genes upregulated in ERBB2 overexpressing luminal breast cancers are indeed PR-driven." (PMID 22697792, 2012). "To overcome these limitations of human BTIC, we've investigated these cells in breast cancer-prone transgenic mice such as those that model ERBB2-positive breast cancer." (PMID 22470504, 2012). "Subgroup analysis of patient survival identified PIK3CA mutation status as an independent prognostic value in patients with ERBB2+ breast cancer." (PMID 22330809, 2012). "ShcA adaptor also plays a critical role in TGF-β- and Neu/ErbB-2-induced breast cancer cell motility and invasion." (PMID 23211466, 2012). "The results show that a number of important cancer genes for each cancer type are ranked highly by TARGETgene, such as AKT1 (rank #1), SRC (rank #10), and ERBB2 (rank #25) in breast cancer." (PMID 22952662, 2012). "Cre-mediated deletion of FAK in established ErbB2 mammary tumour cells resulted in a profound delay in tumour growth that was further associated with a proliferative defect." (PMID 22373082, 2012). "Our current findings suggest that ErbB2 transmembrane mutations (like neu (rat) and the human 655 polymorphism) synergize with decreased/lost PTPN13, allowing breast cancer progression via a mechanism involving increased ErbB2/EphrinB1 signaling." (PMID 22279592, 2012). "We have recently detected MembErbB-2 and NuclErbB-2 in breast cancer cells by IF using the ErbB-2 rabbit polyclonal antibody C-18." (PMID 22356700, 2012). "HER2 (Neu, CD340, ErbB-2) has been effectively targeted in thousands of women with breast cancer using anti-HER2 antibody." (PMID 23251904, 2012). "Overexpression of erbB2 oncogene in breast cancer cells is indicative of highly proliferative tumors with a poor prognosis following conventional chemotherapy." (PMID 22970387, 2012). "Quantitative PCR (qPCR) was performed to verify the expression of breast cancer-related genes (ERα, ErbB2, progesterone receptor (PR), and BRCA1) in each tumor cell lines." (PMID 23140372, 2012).
breast cancer (continued). "SATB1 is known to directly regulate ERBB2, an important regulator of breast cancer progression, in MDA-MB-231 cells." (PMID 23251624, 2012). "International guidelines for ERBB2 (HER2) testing procedures in breast cancer patients highlight the importance of external quality control." (PMID 22448335, 2012). "Following the discovery of ERBB2 gene amplifications in breast cancer, the HER2 receptor became an attractive target for monoclonal antibody-based therapies." (PMID 23033967, 2012). "Survival analysis of a number of genes in this module in six publicly available datasets confirmed they were predictive of better outcome in Basal-like and ERBB2+ breast cancer." (PMID 22789589, 2012). "Memo was initially identified based on its importance in breast cancer cell motility in response to ErbB2 activation, where it was shown to have an essential role in promoting the directionality of motile cancer cells." (PMID 22412880, 2012). "Blocking Pak1 activity, in contrast, inhibits transformation of MCF10A cells by ErbB2 and blocks tumor formation in mice in response to ErbB2 positive breast cancer cell lines." (PMID 23326684, 2012). "We show here a potential initiating role of a complex genomic region in ERBB2 amplification in breast cancer." (PMID 23181561, 2012). "In vitro effects of novel anti-HER2 antibodies were tested against five different breast cancer cell lines displaying different degrees of ERBB2 amplification and HER2 expression." (PMID 23033967, 2012). "Several studies have reported the expression of an ErbB2 alternatively spliced isoform in normal mammary cells and in human breast carcinomas." (PMID 22007291, 2012). "ERBB2 (commonly referred to as HER2) protein overexpression or gene amplification is a predictive marker for response to trastuzumab (Herceptin) in patients with breast cancer (BC)." (PMID 22448335, 2012). "Although generally considered a breast cancer rearrangement, amplification of ERBB2 has also been shown to occur in mucinous ovarian tumors." (PMID 21625565, 2011). "Trastuzumab, the only humanised anti-ErbB2 antibody currently used in breast cancer with success, can engender cardiotoxicity and a high fraction of patients is resistant to Trastuzumab treatment." (PMID 21559015, 2011). "Trastuzumab treatment was able to effectively target tumour-initiating cells of ErbB-2-positive breast cancer cell lines." (PMID 21847123, 2011). "The presence of estrogen receptor (ER), progesterone receptor (PR) and human epidermal growth factor receptor 2 (Her2, also known as ERBB2) is routinely reported in the pathological assessment of breast cancer." (PMID 21939527, 2011). "The accurate assessment of the expression of the estrogen and progesterone hormone receptors (ER and PR) and that of ERBB2 is essential to select the appropriate therapy for breast cancer patients." (PMID 22022496, 2011). "Most notably, 25 to 30 percent of breast cancers overexpress erbB2, and have been targeted for mAb therapy." (PMID 21876697, 2011). "These current findings demonstrate that targeting ER signalling with the pure anti-ER fulvestrant can both suppress and induce gene and protein expression in ER-positive, ErbB2 low-expressing and ErbB2-overexpressing breast cancer cell lines." (PMID 21396094, 2011). "This initial screen demonstrated that GLUT1 was the most abundantly expressed GLUT family member in ErbB2 overexpressing mouse mammary tumors and all five cell lines examined." (PMID 21826239, 2011). "Overexpression of ErbB2 is found in about 30% of breast cancer patients and is correlated with poor prognosis." (PMID 22216158, 2011). "This conclusion suggests that STAT1 has an autonomous role in neu/ERBB2-induced mammary tumor formation." (PMID 22185785, 2011). "The Calu-3 lung adenocarcinoma and BT474 breast cancer cell line, containing high levels of ErbB2, were more sensitive to AST1306, with IC50 values of 0.23 and 0.97 μmol/L, respectively." (PMID 21789172, 2011).
breast cancer (continued). "In breast cancer TFAP2C transactivates the expression of HER-2/neu (ErbB2) and estrogen receptor genes." (PMID 21779369, 2011). "We use a well characterized breast cancer progression model where human-derived MCF10A MECs overexpress either ErbB2, 14-3-3ζ, or both ErbB2 and 14-3-3ζ, with empty vector as a control." (PMID 21647371, 2011). "Although trastuzumab has had a tremendous impact on improving survival for women with ErbB-2-positive breast cancer, resistance to trastuzumab remains a serious and unacceptable clinical problem, particularly in women with metastatic breast cancer." (PMID 21847123, 2011). "ERBB2 is overexpressed in 20–30% of breast cancers, and the monoclonal antibody Trastuzumab (Herceptin) that targets ERBB2 has been used with success to treat these." (PMID 21364580, 2011). "A noticeable point arising from this study is that high levels of NEDD9 expression were associated with the aggressive breast cancers, including TNBC and ERBB2-overexpressing subtypes." (PMID 21829474, 2011). "ERBB2 amplification or overexpression was reported in 30% of breast cancers and is correlated with poor prognosis, increased metastatic potential and resistance to apoptosis." (PMID 22046346, 2011). "Trastuzumab a humanized mAb was approved by the FDA for treatment of breast cancers that overexpress erbB2 in combination with standard chemotherapy." (PMID 21876697, 2011). "The scoring method used here for both EGFR and ERBB2 scoring was chosen because it is extensively and successfully used for ERBB2 in breast cancers in the United Kingdom." (PMID 21364580, 2011). "The final analysis of this study presents a very provocative result, given that the ErbB2 oncogene is detected with lower frequency in invasive and metastatic breast cancers than it is in early stage breast cancers." (PMID 21647371, 2011). "In accordance, they express low levels of ERBB2 (erythroblastic leukemia viral oncogene homolog 2, HER-2/neu) in vivo, the expression and activity of which confer invasive and metastatic ability to breast cancer cells." (PMID 22168360, 2011). "ErbB-2-positive breast cancer is currently treated with therapeutic agents trastuzumab and lapatinib, or current preclinical studies and clinical trials are investigating the combination of trastuzumab plus lapatinib." (PMID 21847123, 2011). "For example, knowledge of the expression of the estrogen and progesterone hormone receptors (ER and PR), and that of the ERBB2 in breast tumor samples enables choice of therapies for the breast cancer patients that express these proteins." (PMID 22022496, 2011). "ErbB3 signalling promotes resistance to tyrosine kinase inhibition in breast cancer cells via heterodimerisation with ErbB2." (PMID 21792199, 2011). "In contrast, ErbB3 localised at the membrane can heterodimerize with other ErbB family members, principally ErbB2, in response to ligand stimulation to potently promote breast cancer cell growth." (PMID 21396094, 2011). "For example, overexpression of active TGF-β1 or active mutant of TβRI (Alk5) in the mammary gland of bigenic mice also expressing mouse mammary tumor virus (MMTV)/Neu (ErbB2) accelerates metastases from Neu-induced mammary cancers." (PMID 21637380, 2011). "ErbB2 is undoubtedly one of the most studied molecules in the field of breast cancer and is a critical target for drug development." (PMID 21647371, 2011). "Our findings are in line with recent reports on the role of STAT1 in the context of ERBB2/neu/HER2 induced mammary cancer development." (PMID 22185785, 2011). "Overexpression of the ERBB2 kinase is observed in about one-third of breast cancer patients and the dual ERBB1/ERBB2 kinase inhibitor lapatinib was recently approved for the treatment of advanced ERBB2-positive breast cancer." (PMID 22046346, 2011). "Breast cancer is a heterogeneous disease, classifiable into five major biologically subtypes, i.e., luminal A, luminal B, basal, ERBB2-overexpressing and normal-like." (PMID 21829474, 2011).